MALAT1 (metastasis associated lung adenocarcinoma transcript 1)
Diseases named in the same sentence as MALAT1 in open-access papers (continued):
Sharing a sentence is not in itself a finding about the gene and the disease.
osteosarcoma (122 papers, 2013 to 2026). A usually aggressive malignant bone-forming mesenchymal neoplasm, predominantly affecting adolescents and young adults. "Another lncRNA that exhibits excessive expression in osteosarcoma is metastasis-associated lung adenocarcinoma transcript 1 (MALAT1), which is also termed nuclear-enriched transcript 2 (NEAT2) and mascRNA." (PMID 39015175, 2024). "Several lncRNAs are overexpressed in osteosarcoma, and one of them is metastasis-associated lung adenocarcinoma transcript 1 (MALAT-1), a lncRNA that controls the recruitment of pre-mRNA-splicing factors to transcription sites." (PMID 37190068, 2023). "For example, upregulated MALAT1 is associated with poor disease-free survival and OS in patients with middle thoracic esophageal squamous cell carcinoma and osteosarcoma." (PMID 36685103, 2022). "Reduced levels of miR-202 in tumor samples and in a metastasis in vivo model indicated that the downregulation of miR-202 expression was associated with lung metastasization of osteosarcoma, driven by the lncRNA MALAT1 sequestering miR-202." (PMID 35682549, 2022). "lncRNA metastasis-associated lung adenocarcinoma transcript 1 (MALAT1) is overexpressed in various cancers, as well as osteosarcoma (OS); however, its underlying mechanism in OS is poorly understood." (PMID 34373692, 2021). "For example, MALAT1 is one of the first identified cancer-associated genes, and it is commonly studied in osteosarcoma." (PMID 34456631, 2021). "Gao and Lian reported that lncRNA MALAT1 was an independent prognostic factor of osteosarcoma, and another lncRNA, H19, was also proved to be associated with osteosarcoma progression." (PMID 34456631, 2021). "Overexpression of MALAT1 was a risk factor of osteosarcoma (HR = 2.15, 95%CI: 1.67–2.76, P < 0.001)." (PMID 33639865, 2021). "The present study aims to analyze the expression of long noncoding RNA (lncRNA) metastasis-associated lung adenocarcinoma transcript 1 (MALAT1) in human osteosarcoma (OS) cells and to investigate its role in OS-induced angiogenesis." (PMID 34692524, 2021). "A recent meta-analysis reported a strong association between high expression of MALAT1 and unfavorable prognosis of patients suffering from osteosarcoma, making it a potential prognostic biomarker for this cancer." (PMID 33430342, 2021). "Recently, scholars explored up-regulation of lnc-MALAT1 (lung adenocarcinoma transcript 1) in osteosarcoma tissues and cell lines, which was significantly associated with poor prognosis." (PMID 32219093, 2020). "Metastasis-associated lung adenocarcinoma transcript 1 (MALAT1) was found to be highly expressed in human osteosarcoma tissue." (PMID 28353666, 2017). "Long non-coding RNA metastasis-associated lung adenocarcinoma transcript 1 (MALAT1) is overly expressed in osteosarcoma." (PMID 28938647, 2017). "We found that MALAT1 had relatively high diagnostic value and predicted poor survival rate in osteosarcoma patients." (PMID 29290978, 2017). "We then analyzed the association between MALAT1 expression with clincopathological factors among the 64 osteosarcoma patients." (PMID 29290978, 2017). "More importantly, one study demonstrated that high MALAT1 was associated with poor response to chemotherapy in osteosarcoma patients." (PMID 29290978, 2017). "In this study, we identified the up-regulation of MALAT1 in primary osteosarcoma tissues or cell lines and further explored its diagnostic and prognostic value." (PMID 29290978, 2017). "MALAT1 knockdown remarkably reduced the formation of tubular network structures and caused the breakage of stress fibers in human osteosarcoma cell lines." (PMID 28353666, 2017). "Metastasis-associated lung adenocarcinoma transcript 1 (MALAT1) is a long non-coding RNA (lncRNA) that contributes to the initiation and development of many solid tumors, including osteosarcoma (OS)." (PMID 27458156, 2016).
osteosarcoma (continued). "Elevated MALAT1 in osteosarcoma tissue have been found to be associated with a late pathological stage, remote tumor deposits, and shortened overall survival, suggesting that this lncRNA could act as an autonomous prognostic factor for this tumor type." (PMID 39015175, 2024). "In addition, the interaction between MALAT1 and LIN28A has been identified in osteosarcoma cells, suggesting potential association of MALAT1 and LIN28A in DN." (PMID 35813614, 2022). "Besides, metastasis-associated lung adenocarcinoma transcript 1 (MALAT1) which is a long noncoding RNA (lncRNA), is elevated in various cancer types such as osteosarcoma, breast, prostate and cervical cancer." (PMID 33849540, 2021). "Similarly, miR-205-5p overexpression is linked to increased proliferation and invasion in ovarian cancer cells, whereas miR-205-5p overexpression was linked to tumor-suppressive effects by decreasing MALAT1 levels in renal cell carcinoma and osteosarcoma." (PMID 31717552, 2019). "Furthermore, the gain and loss function assay showed that miR-205 was suppressed by MALAT1 in osteosarcoma and this interaction between miR-205 and MALAT1 has reciprocal effects." (PMID 29290978, 2017). "Also, MALAT1 has been linked to several other human tumor entities including osteosarcoma." (PMID 28938647, 2017). "For instance, in osteosarcoma, elevated MALAT1 expression is significantly correlated with clinical stage progression and distant metastasis, indicating its potential as an independent predictor of OS in patients." (PMID 41584724, 2026). "The inverse relationship between miR-34a and MALAT1, consistent with a role for MALAT1 as an inhibitor of miR-34a activity, was described in melanoma and osteosarcoma and was also reported with aging in mouse skeletal muscle." (PMID 40863726, 2025). "In osteosarcoma, small interfering RNAs target MALAT-1 to reduce tumor size, suppress tumor proliferation capability, and abrogate its pro-angiogenic effects." (PMID 38201661, 2024). "The upregulation of MALAT1 expression strongly relates to the presence of remote osteosarcoma deposits." (PMID 39015175, 2024). "In osteosarcoma samples, MALAT1 expression was increased, a finding that has a positive association with metastatic deposits in the lungs." (PMID 39015175, 2024). "Since then, several reports confirmed the pro-proliferative activity of MALAT1 toward osteosarcoma cells and showed concomitant inhibition of apoptosis and induction of migration." (PMID 38835012, 2024). "The up-regulated expression of MALAT1 is closely related to the presence of distal osteosarcoma deposits, and the inhibition of MALAT1 can reduce the migration and invasion of osteosarcoma cells." (PMID 39015175, 2024). "In particular, it has been demonstrated that BMSC-EVs-treated osteosarcoma cells showed increased MALAT1 and NRSN2 expressions, and activated Wnt/β-catenin pathway due to MALAT-1 sponging activity versus miR-143." (PMID 38835012, 2024). "The arrest of the cell cycle and apoptosis are both triggered following MALAT1 knockdown, which also leads to the suppression of the growth of osteosarcoma and its dissemination." (PMID 39015175, 2024). "Several studies have confirmed that MALAT1 plays a crucial role in the regulation of multiple signaling pathways in osteosarcoma cells, involving tumor proliferation and metastasis via sponging miRNAs." (PMID 37999460, 2023). "Recent studies reported a positive association between the expression of methyltransferase-like 3 (METTL3) and MALAT1 in osteosarcoma patients." (PMID 38203269, 2023). "In osteosarcomas, MALAT1 is involved in proliferation and metastasis, vasculogenic mimicry, development and regulation of osteosarcoma stem cells, and drug resistance." (PMID 37048099, 2023). "One well-studied long non-coding RNA, MALAT1, plays a crucial role in the regulation of multiple signaling pathways in osteosarcoma cells, involving tumor proliferation and metastasis, resulting in a low proliferation capacity." (PMID 37999460, 2023).
osteosarcoma (continued). "The role of long non-coding RNA MALAT1 in the regulation of multiple signaling pathways in osteosarcoma cells was recently reviewed by Farzaneh." (PMID 37048099, 2023). "Bone marrow-derived mesenchymal stem cell-derived extracellular vesicles (BMSC-EVs) can promote proliferation, invasion, and migration of osteosarcoma cells via the MALAT1/miR-143/NRSN2/Wnt/β-catenin axis." (PMID 36211364, 2022). "Significantly reduced serum miR-425-5p expression makes it a potential prognostic marker in osteosarcoma, and when overexpressed it decreases the expression of very well-known oncogenic lncRNA MALAT1 and TUG1 in addition to suppressed tumor growth in-vivo." (PMID 35755302, 2022). "Other oncogenic lncRNAs such as AFAP-AS1 and MALAT1 (discussed previously) have also been proposed to be a therapeutic target due to their effects on osteosarcoma progression and metastasis." (PMID 35755302, 2022). "In agreement, downregulation of MALAT1 or the upregulation of miR-202 was reported to reduce lung metastasis of osteosarcoma tumors." (PMID 35682549, 2022). "Ectopic expression of MALAT1 increased proliferation, migratory and invasive ability in osteosarcoma cells and promoted tumor growth in mice via sponging miR-129-5p and regulating the RET-Akt pathway." (PMID 35252166, 2022). "Epigenetic regulation of MALAT1 in osteosarcoma has been investigated especially with respect to the expression pattern of EZH2." (PMID 35755302, 2022). "Patients with osteosarcoma (OS) with high levels of MALAT1 expression exhibit a poor prognosis, a high rate of cancer metastasis, and an impact on tumor stage and size." (PMID 35984196, 2022). "For example, a recent study demonstrated the molecular mechanisms of action of the lncRNA named MALAT1, which was found t be upregulated in osteosarcoma." (PMID 36012617, 2022). "In terms of MALAT1, a study suggested that high MALAT1 expression is also associated with advanced clinicopathological features as well as poor prognosis in osteosarcoma, which might emerge as potential therapeutic targets in the treatment of patients with osteosarcoma." (PMID 36440224, 2022). "It has been found that BMSC-derived EVs (BMSC-EVs) promotes the invasion, proliferation and migration of osteosarcoma cells through lncRNA MALAT1/miR-143/NRSN2/Wnt/β-Catenin axis." (PMID 35860555, 2022). "Bone marrow-derived mesenchymal stem cell-derived extracellular vesicles (BMSC-EVs) can promote the proliferation, invasion, and migration of osteosarcoma cells via the MALAT1/miR-143/NRSN2/Wnt/β-catenin axis." (PMID 36211364, 2022). "Recent studies have revealed that some lncRNAs such as lncRNA BC040587, lncRNA TUSC7, and lncRNA MALAT1, which are differentially expressed in osteosarcoma, are involved in the progression of osteosarcoma." (PMID 32960485, 2021). "We found that lncRNA MALAT1 and miR‐329‐5p were present in osteosarcoma and regulated proliferation and metabolism of osteosarcoma cells." (PMID 33939272, 2021). "Recently, a long non-coding RNA (lncRNA) MALAT1 was reported to be upregulated in lung metastatic osteosarcomas." (PMID 34386496, 2021). "Downregulation of MALAT1 as a ceRNA for miR-144-3p inhibited tumor cell invasion by reducing the expression of ROCKI/ROCKII in osteosarcoma cells." (PMID 34771549, 2021). "Herein, we screened 6 osteosarcoma-related genes by lncRNA microarray, MALAT1, HCG9, FAM99A, FAM87B, DLEU2, and C8orf49." (PMID 34456631, 2021). "An elevated expression of MALAT1 was observed in osteosarcoma patients, and correlated with poor prognosis." (PMID 34771549, 2021). "Their high expression predicted poor prognosis of osteosarcoma (MALAT1 (HR = 2.15, 95%CI: 1.67–2.76, P < 0.001), TUG1 ((HR = 2.41, 95%CI: 1.42–4.07, P = 0.001), XIST (HR = 1.79, 95%CI: 1.40–2.30, P < 0.001), NEAT1 (HR = 1.96, 95%CI: 1.05–3.68, P = 0.035))." (PMID 33639865, 2021).
osteosarcoma (continued). "Six genes presented statistically significant expressions (P < 0.05) in osteosarcoma tissues versus paracarcinoma tissues and were screened, which were MALAT1, HCG9, FAM99A, FAM87B, DLEU2, and C8orf49." (PMID 34456631, 2021). "We found elevated MALAT1 levels in osteosarcoma patients and these levels were ~ 7 times higher in the patients." (PMID 32728178, 2020). "MALAT1 was also high in osteosarcoma cells KRIB and MALAT1’s targeted downregulation in these cells led to decreased invasive potential and identification of miR-202 as the miRNA that is sponged by MALAT1." (PMID 32728178, 2020). "In osteosarcomas, MALAT1 increased stem cell-like properties by regulating the expression of RET via sponging miR-129-5p." (PMID 32377169, 2020). "FOXO1 has been reported to negatively regulate MALAT1 by binding to its promoter in osteosarcoma cells." (PMID 32708561, 2020). "For performing experiments to study mechanism, we evaluated MALAT1 levels in several osteosarcoma cell lines so as to find the most appropriate model." (PMID 32728178, 2020). "For example, nine lncRNAs (91H, FGFR3-AS1, BCAR4, TUG1, UCA1, HIF2PUT, HOTTIP, HULC, and MALAT-1) are up-regulated in osteosarcoma, which is considered oncogenic for osteosarcoma." (PMID 31850493, 2020). "It is possible that targeted downregulation of MALAT1 or the upregulation of miR-202 can reduce lung metastasis of osteosarcoma." (PMID 32728178, 2020). "FOXO1 was also reported to negatively regulate MALAT1 by binding to its promoter in osteosarcoma cells." (PMID 32708561, 2020). "This assumption was based on the inverse relationship between MALAT1 and miR-202 and the elevated levels of MALAT1 in osteosarcoma patients with lung metastasis." (PMID 32728178, 2020). "To establish a mechanistic working model, we next checked for levels of MALAT1 in the osteosarcoma cell lines." (PMID 32728178, 2020). "MALAT1 can regulate target genes by acting as a “sponge” of some miRNAs, miR-144-3p in osteosarcoma cells that are regulated by MALAT1 function as competing endogenous RNAs (ceRNAs)." (PMID 33274006, 2020). "The results of this study suggested that lnc-MALAT1 increased osteosarcoma proliferation and metastasis by competitively binding to miR-34a/c-5p and miR-449a/b." (PMID 32219093, 2020). "After establishing a possible involvement of lncRNA MALAT1 in lung metastasis of osteosarcoma and finding possible miRNA targets of MALAT1, we turned to in vivo models for further verification." (PMID 32728178, 2020). "To further evaluate the role of MALAT1-miR-202 axis, we downregulated miR-202 in MALAT1 downregulated osteosarcoma cells while conducting the in vivo studies." (PMID 32728178, 2020). "In our study, we also found MALAT1 levels to be higher in osteosarcoma, compared to healthy individuals which means that MALAT1 can not only serve as biomarker for lung metastasis but as a possible diagnostic marker for osteosarcoma." (PMID 32728178, 2020). "Our results indicated MALAT1 to be the most dysregulated lncRNA in osteosarcomas with lung metastasis." (PMID 32728178, 2020). "It needs to be mentioned that while we found MALAT1 to be upregulated in metastatic osteosarcomas and that an oncogenic role of MALAT1 in osteosarcoma is supported by many reports, there are indications of a tumor suppressive role of MALAT137." (PMID 32728178, 2020). "In summary, we provide evidence for a role of MALAT1 in lung metastasis of osteosarcomas which involves regulation of miR-202." (PMID 32728178, 2020). "MALAT-1, metastasis-associated lung adenocarcinoma transcript 1, enhanced PI3K/AKT activation and led to osteosarcoma metastasis." (PMID 32404870, 2020). "FOXO1 has been reported as a transcriptional factor of MALAT1 that negatively regulates MALAT1 in osteosarcoma cells." (PMID 32708561, 2020). "Some recent studies have highlighted MALAT1 as a sponge lncRNA for miR-205 in cells including renal carcinoma, osteosarcoma, and neuronal cells." (PMID 31866580, 2019).
osteosarcoma (continued). "A previous study reported that FOXO1-related lncRNA MALAT1 can inhibit osteosarcoma cell proliferation, indicating the presence of a class of lncRNAs regulated by FOXO1, which play important roles in PDAC progression." (PMID 31027497, 2019). "(2016) found that the level of long noncoding RNA (lncRNA) MALAT1 in osteosarcoma tissues was higher than that in paired adjacent normal tissues, and it affects the invasion and metastasis abilities of osteosarcoma cells." (PMID 31044561, 2019). "MALAT1 (Metastasis associated in lung adenocarcinoma transcript 1) increases protein levels of RhoA and the downstream ROCK in osteosarcoma." (PMID 31248165, 2019). "It is interesting that Wang and Sun have demonstrated that MALAT1 contains a target site of miR-26a-5p and MALAT1 directly regulates miR-26a-5p in osteosarcoma cells." (PMID 31143769, 2019). "Specifically, the interaction between MALAT1 and miR-205 has been demonstrated in different cell types, including renal carcinoma, osteosarcoma, and neuronal cells." (PMID 31866580, 2019). "MALAT1 exerted its oncogenic function in osteosarcoma as a ceRNA to suppress miR-34a expression and upregulate CCND1." (PMID 31143769, 2019). "Knockdown of MALAT-1 results in decreased cell proliferation and migration by inducing cell cycle arrest from the G0/G1 to S-phase and apoptosis in osteosarcoma cell lines U2OS and HOS." (PMID 29657304, 2018). "High expression of MALAT1 was closely correlated with pulmonary metastasis in patients with osteosarcoma." (PMID 29441193, 2018). "In osteosarcoma cells, downregulation of MALAT-1 inhibits PI3K/Akt signalling, whereas in breast and ovarian cancer cells, knockdown of MALAT-1 knockdown results in increased PI3K/Akt signalling and induction of EMT." (PMID 29701689, 2018). "Other than MALAT-1 and PANDA, lncRNA Cancer susceptibility candidate 2 (CASC2) is significantly downregulated both in human osteosarcoma tissue and osteosarcoma cell lines MG-63, U2OS, SAOS2, and SOSP-9607 (p < 0.01)." (PMID 29657304, 2018). "MALAT1 is frequently upregulated in osteosarcoma (OS) primary tissues and cell lines, and the analysis of clinical samples demonstrated correlation of high serum levels of MALAT1 with reduced survival rate in OS patients." (PMID 29739426, 2018). "MALAT1 was observed to promote malignancy in osteosarcoma, as its knockdown inhibited cell proliferation and invasion, and suppressed metastasis." (PMID 28412742, 2017). "For osteosarcoma, previous reports revealed that MALAT1 was also upregulated in primary tissues and cell lines, and high MALAT1 expression level confers a poor prognosis." (PMID 29290978, 2017). "In our current study, we sought to identify the regulatory role of MALAT1 in osteosarcoma cell proliferation, and further identify the direct target correlated with the malignant phenotype of osteosarcom." (PMID 29290978, 2017). "This study confirmed that the expression of MALAT1 was up-regulated in both human osteosarcoma cell lines and tissues, and knockdown of MALAT1 delayed the tumor growth in vivo." (PMID 29245999, 2017). "The present study demonstrated that MALAT1 was significantly up-regulated and predicted poor outcome in osteosarcoma." (PMID 29290978, 2017). "In conclusion, our integrated approach demonstrated that MALAT1 was up-regulated and conferred a poor prognosis in osteosarcoma patients." (PMID 29290978, 2017). "More importantly, MALAT1 promoted osteosarcoma cell proliferation through suppressing miR-205 and activating SMAD4 signaling." (PMID 29290978, 2017). "MALAT1 was up-regulated in all the four osteosarcoma cell lines compared with normal osteoblastic cells." (PMID 29290978, 2017). "Further research also indicated that the knockdown of MALAT1 by siRNA significantly inhibited the migration of human osteosarcoma cell lines." (PMID 28353666, 2017).